CYP2E1 (cytochrome P450 family 2 subfamily E member 1)
Diseases named in the same sentence as CYP2E1 in open-access papers (continued):
Sharing a sentence is not in itself a finding about the gene and the disease.
gastric cancer (continued). "In the present case-control study, for CYP2E1 PstI polymorphism, we observed that both C2 carriers and C2C2 genotypes were significantly associated with gastric cancer risk and poor clinical prognosis." (PMID 22957075, 2012). "No studies have investigated the association of ADH1C or CYP2E1 polymorphisms with multiple gastric cancers." (PMID 39063094, 2024). "Overexpression of CYP2E1 in gastric cancer cells enhanced proliferation, invasion, and survival." (PMID 33659048, 2021). "For CYP2E1 PstI/RsaI polymorphism, C2C2 homozygotes (OR = 2.15; CI: 1.18–3.94) and C2 carriers (OR = 1.48; CI: 1.13–1.96) were associated with an increased risk of gastric cancer when compared with C1C1 homozygotes." (PMID 22957075, 2012). "Moreover, there has been no report on the association between CYP2E1 polymorphism and survival of patients with gastric cancer." (PMID 22957075, 2012). "This may explain why the PstI/RsaI, rather than DraI, polymorphism of CYP2E1 conferred a greater risk of gastric cancer in this study." (PMID 22957075, 2012). "However, there was not any significant association between CYP2E1 DraI polymorphism and the risk of gastric cancer." (PMID 22957075, 2012). "However, we did not found any significant association between CYP2E1 DraI polymorphism and both gastric cancer risk and clinical prognosis." (PMID 22957075, 2012). "The results showed that CYP2E1 RsaI/PstI polymorphisms may not be correlated with gastric cancer risk." (PMID 23139769, 2012). "In this study, the presence and cellular localization of several major forms of P450, CYP1A, CYP2E1 and CYP3A have been investigated in stomach cancer and compared with their expression in normal stomach." (PMID 9569036, 1998). "Distribution of CYP2E1 RsaI/PstI genotype among ever-smokers and never-smokers bearing gastric cancers in the meta-analysis." (PMID 23139769, 2012). "In CYP2E1 PstI restriction analysis, both C1C2 and C2C2 genotypes were associated with advanced stage, but not the grade of gastric cancer." (PMID 22957075, 2012). "In addition, our meta-analysis also confirmed that the CYP2E1 PstI polymorphism, but not DraI, was associated significantly with the risk of gastric cancer, which provided further evidence indicating an association between this functional polymorphism and gastric cancer susceptibility." (PMID 22957075, 2012). "Distribution of CYP2E1 RsaI/PstI genotype among ever-drinkers and never-drinkers bearing gastric cancers in the meta-analysis." (PMID 23139769, 2012).
non-alcoholic steatohepatitis (12 papers, 2012 to 2025). "Consistent with this view, the CYP2E1 isoenzyme has been implicated in a variety of pathological conditions such as diabetes, non-alcoholic steatohepatitis (NASH) and cancer, possibly as a result of its capacity to produce high levels of reactive oxygen species (ROS)." (PMID 24207099, 2013). "We have already shown that our newly developed CYP2E1 inhibitor 12-imidazolyl-1-dodecanol (I-ol) was therapeutically effective against alcoholic and nonalcoholic steatohepatitis." (PMID 33604316, 2021). "In particular, Chen and coworkers showed how geraniol was able to ameliorate non-alcoholic steatohepatitis (NASH) induced by methionine-choline-deficient (MCD) diet in rats, also via CYP2E1 inactivation." (PMID 29422862, 2018). "Hepatic CYP2E1 has been linked to the pathogenesis of ASH (alcoholic steatohepatitis), hepatic steatosis and NASH (non-alcoholic steatohepatitis)." (PMID 23577625, 2013).
colorectal cancer (10 papers, 2007 to 2024). A primary or metastatic malignant neoplasm that affects the colon or rectum. "A model HCC cell line (HepG2 cells) and a model colorectal cancer cell line (DLD-1 cells) were used because the development and progression of both diseases are associated with CYP2E1." (PMID 33604316, 2021). "Accordingly, previous studies have commonly focused on ADH1B, ADH1C, ALDH2, CYP2E1, and MTHFR genotypes as modifiers of the association between alcohol consumption and risk of alcohol-related cancers, including colorectal cancer." (PMID 29464080, 2018). "Our objective was to measure the interactions between common polymorphisms of P450 (CYP1A2, CYP1B1, CYP2E1), GSTM1 and T1, SULT1A1 and cigarette smoking in colorectal cancer (CRC)." (PMID 17603900, 2007). "Only three upregulated genes (APOC1, CYP2E1, HPR) were significant in term of prognosis, suggesting that these three genes could be associated with prognosis in colorectal cancer patients." (PMID 34081622, 2021). "In T84 cells, which are derived from human colorectal carcinoma and thought to be a potential alternative to Caco-2 cells, the expression of CYP3A4 is controversial, while expressions of CYP2B6, CYP2C9, CYP2C19, and CYP2E1 are lacking." (PMID 34604364, 2021).
fibrosis (9 papers, 2009 to 2025). the formation of excess fibrous connective tissue in an organ or tissue in a reparative or reactive process. "As CYP2E1 activity is significantly increased in fibrosis patients, we speculated that CYP2E1 is a risk factor for liver injury and fibrosis induced by nitrosamines." (PMID 29348818, 2017). "The theophylline fraction of Σcaffeine was significantly increased with both fibrosis and the FLI, possibly reflecting elevated CYP2E1 activity—a hallmark of NAFLD worsening." (PMID 36615664, 2022). "We observed a higher V for DEN in the fibrosis patients than in the normal subjects (P=5.3E-13), which was similar to the pattern observed for chlorzoxazone (a probe substrate for CYP2E1) metabolism (P=2.6E-12)." (PMID 29348818, 2017). "Elevated CYP2E1 expression was also described in liver of chronic hepatitis C patients with mild fibrosis." (PMID 27200149, 2016). "Levels of CYP2E1 mRNA are known to be elevated in biopsies of hepatitis C patients with mild fibrosis." (PMID 26035647, 2015).
Parkinson disease (9 papers, 2012 to 2025). A progressive degenerative disorder of the central nervous system characterized by loss of dopamine producing neurons in the substantia nigra and the presence of Lewy bodies in the substantia nigra and locus coeruleus. "Increased ROS production is observed in the substantia nigra when substrates for CYP2E1 are present, and a mutation in the CYP2E1 gene is associated with Parkinson’s disease." (PMID 23049996, 2012). "Multiple epigenome-wide association studies (EWAS) in Parkinson's disease (PD) have revealed significant DNA methylation changes in genes, such as CYP2E1, SNCAIP, and several others across various brain regions, implicating pathways, such as Wnt and Hippo, in PD pathology." (PMID 38995454, 2024). "Clinical studies of Parkinson's disease (PD) show that environmental factors, xenobiotics, including chemicals, pesticides, and volatile solvents are the most suspected causes, all of which are substrates of CYP2E1." (PMID 28163821, 2017). "Furthermore, dysmethylation of CYP2E1 was observed in Parkinson’s diseased brains." (PMID 36494682, 2022). "Also, GDAs showed that CYP2E1 and CYP3A5 trigger common diseases with CYP2D6 such as ADRs, Drug Allergy, Chemical and drug-induced liver injury, Parkinson’s disease, Schizophrenia, and Mood disorders." (PMID 39505757, 2024). "The CYP2E1 enzyme can metabolize ethanol to acetaldehyde, a highly reactive and toxic compound, which can enhance the 1-methyl-4-phenyl-1,2,3,6-tetrahydropyridine (MPTP) -induced parkinsonism in mice." (PMID 32230811, 2020). "Furthermore, the methylation of candidate genes and cytochrome P450 2E1 (CYP2E1) in DNA from blood mononuclear cells from 259 Parkinson’s disease patients and 182 healthy controls, as well as skin fibroblasts from 10 Parkinson’s disease patients and 5 healthy controls, were compared." (PMID 38239489, 2023).
liver failure (8 papers, 2016 to 2024). A liver disease characterized by the liver losing or has lost all of its function. "Research has demonstrated that toxins are metabolized by enzymes like Cytochrome P450 2E1 (CYP2E1) and converted into reactive species, causing oxidative damage and liver failure." (PMID 39508089, 2024). "Overall, it has been suggested that “the cisplatin and CYP2E1 interaction leads to the generation of ROS and other oxidants resulting in renal injury; and that ROS generated by both the use of cisplatin and by the CYP2E1 increases tissue damage, induces apoptosis, and causes liver failure”." (PMID 31756937, 2019). "CCl4 is preferentially converted into toxic free radicals through CYP2E1, leading to oxidative injury in the liver, which is likely to develop into liver failure." (PMID 37175256, 2023). "The CYP2E1 expression trend was confirmed at the mRNA level, suggesting SCEO pre-treatment attenuates CYP2E1 to suppress APAP-induced liver failure." (PMID 35588406, 2022). "Previous studies find the therapeutic effects of MSCs on APAP-induced liver failure by inhibiting CYP2E1 activity, maintaining GSH levels and increasing antioxidant enzyme activity." (PMID 35246254, 2022). "T. crassiceps infection increases CYP2E1 expression in the acetaminophen-inducedacute liver failure murine model - In hepatocytes, acetaminophen ismetabolised by the cytochrome P450 family 2 subfamily E member 1 (CYP2E1)." (PMID 27812602, 2016). "Additionally, in the sera from patients with INH-induced liver failure, antibodies against CYP2E1 modified by INH were found, and INH was found to form covalent adducts with CYP2E1, CYP3A4, and CYP2C9 in vitro." (PMID 30873473, 2017). "The reported pharmacokinetic study suggested that CYP2E1 was the most stable enzyme, whereas CYP2C19 (with CYP1A1 and CYP2D6 in the middle) was the most vulnerable in liver failure." (PMID 34575411, 2021). "The published clinical pharmacokinetic studies suggest that liver failure can affect CYP1A2, CYP2C19, CYP2D6, CYP2E1 and CYP3A4 activities." (PMID 34575411, 2021).
metabolic syndrome (8 papers, 2013 to 2025). A cluster of metabolic risk factors for CARDIOVASCULAR DISEASES and TYPE 2 DIABETES MELLITUS. "Our results showed that cg11445109 and cg19469447 (annotated to CYP2E1 gene) were significantly more hypomethylated in patients who improved their metabolic status compared to those who remained with metabolic syndrome after bariatric surgery." (PMID 37834223, 2023). "The expressions of CYP2C, CYP2E1, and CYP3A are influenced by metabolic syndrome." (PMID 31396457, 2019).
ovarian carcinoma (8 papers, 2017 to 2023). A malignant neoplasm originating from the surface ovarian epithelium. "Identification of stronger associations between acrylamide and ovarian cancer in genetically susceptible individuals (e.g., of a certain CYP2E1 genotype) increases confidence that the observed association between acrylamide intake and ovarian cancer is not due to chance or bias." (PMID 28391539, 2017). "Importantly, a marked increase in CYP2E1 activity was found in the sera of ovarian cancer patients." (PMID 38001897, 2023). "This speculation is supported by previous reports from other groups as well as ours that increased CYP2E1 activity is closely associated with oxidative stress, inflammation, and inflammation-related diseases like nonalcoholic steatohepatitis (NASH), hepatofibrosis, HCC, ovarian cancer, and so on." (PMID 35164791, 2022). "Considering the apparent scarcity of investigations and their limited sample sizes, studies on the polymorphisms of the CYP2D6, CYP2E1, and CYP3A5 genes demonstrate a lack of genotype associations with ovarian cancer susceptibility." (PMID 38001897, 2023).
type 2 diabetes (8 papers, 2018 to 2025). "Regarding CYP2E1 expression, it is noteworthy that this enzyme is significantly over-expressed in Type 2 diabetics, potentially putting them at increased risk to the genetic effects of NDMA." (PMID 36992846, 2023). "One DMR was located in the promoter of OR2L13 which has been associated with autism spectrum disorders, and the other was located in the gene body of CYP2E1 which has been implicated in type 1 and type 2 diabetes." (PMID 35721735, 2022). "This overexpressed CYP2E1 exhibits a high capacity to produce free radicals that are probably the cause of liver damage and lipid peroxidation in obese type 2 diabetes patients." (PMID 33261113, 2020).
hepatitis C (7 papers, 2014 to 2025). "NADPH oxidases and CYP2E1 serve as the major sources of ROS in infections with human hepatitis C, influenza, and respiratory syncytial viruses." (PMID 38790623, 2024). "NADPH oxidases and cytochrome P450 2E1 (CYP2E1) serve as the major sources of ROS in hepatitis C, influenza, and HIV." (PMID 33172001, 2020).
toxicity (7 papers, 2013 to 2022). The degree to which an agent can damage an organism. "For example, among Indian pediatric patients the risk of liver toxicity was enhanced by a variant in the CYP2E1 gene, while the SLCO1B1rs4149032 polymorphism was associated with low-level rifampin exposure." (PMID 26402689, 2015). "Delivery of CYP2E1 to these cells has the potential to increase the local concentration of CYP2E1, which would further increase the metabolism of alcohol and APAP causing alcohol-induced and APAP-induced brain toxicity." (PMID 36078027, 2022). "Increasing amounts of evidence have indicated that CYP2E1-dependent ER stress contributes substantially to the pathogenesis of radiation-induced pulmonary fibrosis and environmental toxicant-induced liver toxicity." (PMID 33967806, 2021). "Among many phytochemicals showed hepatoprotective against APAP few of them found to inhibit CYP2E1 that could be promising for further evaluation in APAP-induced liver toxicity." (PMID 30486484, 2018). "CYP2E1 is a key enzyme that metabolizes xenobiotics and can trigger a series of events that lead to APAP-induced liver toxicity." (PMID 31214283, 2019).
alcohol abuse (6 papers, 2018 to 2024). The use of alcoholic beverages to excess, either on individual occasions ("binge drinking") or as a regular practice. "It has been suggested that chronic alcohol abuse increases susceptibility to paracetamol toxicity due to CYP2E1 induction, that hepatic GSH is reduced leading to reduced NAPQI detoxification and/or that glucuronidation is reduced leading to increased fractional oxidation." (PMID 29067481, 2018). "Cytochrome P450 2E1 (CYP2E1) is pivotal in hepatotoxicity induced by alcohol abuse and different xenobiotics." (PMID 35053404, 2022). "Generally, CYP2E1 is up-regulated in chronic alcohol abuse conditions and leads to converting more alcohol to acetaldehyde." (PMID 31159489, 2019). "Indeed, CYP2E1 is central to the occurrence of different acute and chronic liver diseases induced by drugs, toxicants and alcohol abuse." (PMID 35053404, 2022). "We believe this to be the first detailed functional description of increase collagen synthesis during INH treatment in presence of CYP2E1 inducer and the connotations of the findings are fairly wide particularly in patients having alcohol abuse, intake of high fat diet and concomitant use of drugs." (PMID 32735603, 2020). "However, it is increased in chronic alcohol abuse conditions due to the induction of the expression of CYP2E1." (PMID 31159489, 2019). "APAP toxicity is also observed in people with alcohol use disorder (AUD), possibly due to upregulated CYP2E1 activity or a response to fasting (which is known to decrease GSH levels and increase CYP2E1)." (PMID 38214802, 2024). "Cytochrome P450, in particular, cytochrome P450 2E1 (CYP2E1), is upregulated in chronic alcohol abuse and assists ADH in the conversion of alcohol to acetaldehyde." (PMID 37375652, 2023).
colon cancer (6 papers, 2018 to 2023). "Cyp2e1 mRNA expression was modestly decreased at high dietary selenium levels in untreated control animals, and appeared to positively correlate with increasing dietary selenium in colon tumors of AOM/DSS-treated animals." (PMID 34638991, 2021). "In the human digestive system, the expression of CYP2E1 and GSTK1 was found to be higher in both the gastric and colon tumor tissues." (PMID 36766250, 2023). "Supportive signs of evidence suggest that EtOH is able to increase ROS level in different cell lines, including colon cancer cells, through both ADH and CYP2E1 activity." (PMID 30974805, 2019). "First, the role and mechanism of CYP2E1 in colon cancer were not further explored in this study, for example, cell functional assays need to be performed to investigate the effects of CYP2E1 on the proliferation, migration, and invasion of CC cells." (PMID 36313348, 2022).
Hypertension (6 papers, 2019 to 2025). The presence of chronic increased pressure in the systemic arterial system. "In addition, numerous loss-of-function gene promoter polymorphisms in Cyp2e1 have been identified in humans, and these mutations have been clinically associated with essential hypertension in men57." (PMID 33127986, 2020). "Overall, the sex-specific effects seen in PAH, SLC9A3 and CYP2E1 genes likely play an important role in sex-specific responses to prenatal stress, and a comprehensive study needs to be undertaken to examine their role in the programming of hypertension." (PMID 31483805, 2019). "Thus, its interactions with alcohol-inducible CYP2E1 may shed light on the mechanisms of alcohol-induced hypertension." (PMID 35204686, 2022).
lipid metabolism disorders (6 papers, 2018 to 2024). "We selected oxidative stress and apoptosis-related proteins Fas and cytochrome C, inflammation-related proteins P65 and JNK1/2, lipid metabolism disorder-related proteins SREBP1 and leptin, and insulin resistance-related proteins GSK3β and CYP2E1 for subsequent experimental validation." (PMID 35845577, 2022).
prostate carcinoma (6 papers, 2008 to 2025). A carcinoma that arises from epithelial cells of the prostate gland. "Indeed, it was found in the Portuguese population that the CYP2E1 gene could be associated with prostate cancer risk." (PMID 18423013, 2008). "We also identified multiple prostate cancer-associated genes such as cystatin C, PSCA, Cyp2e1, and dermatopontin that were remarkably underexpressed in CTRKO/LPB-Tag-CTRKO as compared to their WT and LPB-Tag counterparts, suggesting that CTR positively regulates these genes." (PMID 32180899, 2020). "CYP2E1 is involved in xenobiotic detoxification but is also a driver of ROS production; FGFR1 is linked to proliferation and treatment resistance; and GSTM2 has been identified in antioxidant defense and has been associated with resilience to treatment and OS-induced stress in prostate cancer." (PMID 41009689, 2025).
alcoholic cirrhosis (5 papers, 2013 to 2021). "It has been hypothesized that ethanol produced by microbiota fermenting dietary sugars could cause dysbiosis, increased CYP2E1 levels and nitroxidative stress in NAFLD patients and maybe endotoxin levels are thus lower in patients with alcoholic cirrhosis compared with non-alcoholic cirrhosis." (PMID 34360999, 2021).
autism spectrum disorder (5 papers, 2021 to 2024). A spectrum of developmental disorders that includes autism, and Asperger syndrome. "Recently, the methylation at CYP2E1 was found to be associated with both autism spectrum disorder and expression differences in brain." (PMID 36494682, 2022). "One region covering the promoter of OR2L13, a gene associated with autism spectrum disorder, and the other one covering the cytochrome P450 family 2 subfamily E member 1 (CYP2E1) gene, which is upregulated in type 1 and T2D." (PMID 36452324, 2022).